MIR521-1 (microRNA 521-1)
Synonyms: hsa-mir-521-1; MIRN521-1; mir-521-1
Gene: MicroRNA gene on chromosome 19 (53,748,636 to 53,748,722, forward strand). Ensembl gene ENSG00000207634.
Gene Ontology:
Biological process: miRNA-mediated post-transcriptional gene silencing
Homologues: Orthologues: chimpanzee ptr-mir-521-1 (100% identical), macaque mml-mir-521 (95% identical). Paralogues in human: MIR518E (87% identical), MIR523 (87% identical), MIR524 (87% identical), MIR517A (85% identical), MIR518C (85% identical), MIR518F (85% identical), MIR520C (85% identical), MIR516A1 (84% identical), MIR518D (84% identical), MIR519A2 (84% identical), MIR520F (84% identical), MIR522 (84% identical), and 12 more.